MTND2P13 (MT-ND2 pseudogene 13)
Gene: Unprocessed pseudogene on chromosome 17 (22,525,899 to 22,526,937, forward strand). Ensembl gene ENSG00000263914.
Diseases named in the same sentence as MTND2P13 in open-access papers:
MTND2P13 is named in the same sentence as 1 disease in open-access papers, as found by Europe PMC text mining. Sharing a sentence is not in itself a finding about the gene and the disease. The quoted sentences say what the papers report.
neoplasm (1 paper, 2024). A benign or malignant tissue growth resulting from uncontrolled cell proliferation. "CKS1B+ neoplasm, C16orf89+ neoplasm, CST6+ neoplasm, H2AC6+ neoplasm and MTND2P13+ neoplasm all demonstrate heightened tumour stemness." (PMID 38946232, 2024). "CKS1B+ neoplasm, CST6+ neoplasm and MTND2P13+ neoplasm are more prevalent in advanced LUAD, while DLX5+ neoplasm is more common in early‐stage LUAD." (PMID 38946232, 2024).